IL1B (interleukin 1 beta)
Diseases named in the same sentence as IL1B in open-access papers (continued):
Sharing a sentence is not in itself a finding about the gene and the disease.
myocardial infarction (continued). "Great interest has been aroused by the effect of a therapeutic monoclonal antibody targeting IL-1β, canakinumab, whose administration led, in a large cohort of patients with previous myocardial infarction, to a significantly lower rate of recurrent cardiovascular events." (PMID 35486344, 2022). "Moreover, decreases in the levels of TNF-α and IL-1β, and increases in IL-10, were also shown in a rat model of myocardial infarction." (PMID 35161351, 2022). "The canakinumab anti‐inflammatory thrombosis outcomes (CANTOS) study has shown that antagonism of IL‐1β reduces recurrent myocardial infarction in patients with plasma C‐reactive protein (CRP) levels >2 mg/L, suggesting an important role for IL‐1β induced inflammation in CVD." (PMID 35833096, 2022). "Table. demonstrates the animal studies of RIC and cytokine release, performed within the last 5 years, following myocardial infarction and reperfusion Across several studies, RIC was associated with reduced levels of the pro-inflammatory cytokines, IL-1β, TNF-α and HMGB1 following reperfusion." (PMID 33629195, 2021). "Moreover, IL1B can aggravate ischemia-reperfusion injury and cardiac remodeling after experimental myocardial infarction." (PMID 34169069, 2021). "In a large RCT of patients with prior myocardial infarction and elevated high-sensitivity C-reactive protein, the IL-1β antagonist canakinumab 150 mg demonstrated benefit vs. placebo for a composite end point of myocardial infarction, stroke, or cardiovascular death." (PMID 34698811, 2021). "Circulating CD14+HLA-DRneg/low monocytes secrete high levels of TNFα, IL-6, and IL-1β which promote proinflammatory immune responses; in the expansion of this monocyte population after myocardial infarction correlates with both cardiac damage and physiological function." (PMID 34589791, 2021). "This notorious phase III, placebo-controlled, randomized trial tested the monoclonal antibody anti-IL-1β canakinumab at the dosage of 50 mg, 150 mg and 300 mg every 3 months in subjects with previous myocardial infarction and baseline levels of high-sensitive C reactive protein (hs-CRP) ≥ 2 mg/L." (PMID 33770265, 2021). "Previous studies have demonstrated that MCC950 treatment could reduce IL-1β production and attenuate the severity of lung ischemia-reperfusion injury, ulcerative colitis, myocardial infarction, multiple sclerosis, and liver transplantation." (PMID 34869447, 2021). "Similarly, studies using the NLRP-3 inflammasome inhibitor, MCC950, resulted in slowing the development of HF in both models of myocardial infarction (MI) and pressure overload by suppressing IL-1β release." (PMID 32604981, 2020). "Many molecules like troponins, brain natriuretic protein (BNP), ST2/IL-33, C-reactive protein (CRP), TNF, IL-1β, and IL-18 cytokines have been already examined as molecular markers for diagnosing or predicting different cardiac disturbances like myocardial infarction, heart failure, or myocarditis." (PMID 33172097, 2020). "The CANTOS (Canakinumab Antiinflammatory Thrombosis Outcome Study) trial assessed the efficacy of the anti-IL1β human monoclonal antibody canakinumab to prevent vascular events in patients with previous history of myocardial infarction and presenting high levels of hsCRP marker." (PMID 32574952, 2020). "For example, recent clinical trials found an anti-inflammatory Canakinumab, a monoclonal antibody for IL-1β, significantly reduced incidence of recurrent cardiovascular events as well as lung cancer in patients with previous myocardial infarction and elevated CRP." (PMID 31644575, 2019). "Similarly, CANTOS demonstrated that IL-1β blockade reduces recurrent myocardial infarction in human after ACS." (PMID 31779200, 2019). "Finally, treatment with β-caryophyllene reduces the levels of the inflammatory markers TNF-α, IL-1β, and NFκB in heart tissue, which are elevated in isoproterenol-induced myocardial infarction." (PMID 31109132, 2019).
myocardial infarction (continued). "The astonishingly reduction of incident lung cancer cases among patients with prior myocardial infarction treated with the anti-IL-1b antibody (canakinumab) in lung cancer are indeed opening a new scenario for the crucial role of the IL-1 cytokine in cancer development." (PMID 30261609, 2018). "Consistent unfolding of the intricate links between MetS, inflammation and pathogens may further point at novel therapeutic avenues; one recent example is anti-IL-1β antibodies investigated for secondary prevention of myocardial infarction." (PMID 29922126, 2018). "NLRP3 inflammasome-activated NLRP3/ASC-dependent inflammatory responses result in the release of significant amounts of caspase-1 and IL-1β, and these innate immune responses play an important role in diabetic cardiomyopathy, myocardial infarction, and MI/R injury." (PMID 29062465, 2017). "Indeed, IL-1β enhances hematopoietic stem cell proliferation and leukocyte production after acute myocardial infarction in mice and is reduced by administration of anti–IL-1β antibodies." (PMID 27737744, 2016). "IL-1β is considered a key inflammatory mediator after acute myocardial infarction." (PMID 25202335, 2014). "In addition, fibrin beta decreases myocardial infarct size, scar formation, inflammation and the levels of cytokines (interleukin 1 beta, tumor necrosis factor-alpha and interleukin 6) in plasma." (PMID 23139772, 2012). "In our previous research, we synthesized three variable heavy chain-only antibodies (VHHs) and validated their affinity for IL-1β, as demonstrated in mouse and rat myocardial infarction (MI) models." (PMID 39811465, 2025). "CANTOS demonstrated for the first time that targeted inhibition of inflammation (by blocking IL-1β) reduces the risk of recurrent cardiovascular events in patients with previous myocardial infarction and residual inflammation, independent of cholesterol lowering." (PMID 41511355, 2025). "In addition, IL-1β blockade (e.g., with anakinra) has been trialed in post-myocardial infarction remodeling and could be explored in transplant settings." (PMID 41009699, 2025). "In summary, the findings of this study indicate that 4G6M-VHH effectively neutralizes IL-1β, presenting a potential therapeutic target for myocardial infarction (MI) treatment." (PMID 39811465, 2025). "In CANTOS (Canakinumab Anti-inflammatory Thrombosis Outcomes Study), an IL-1β monoclonal antibody canakinumab was investigated in post-myocardial infarction (MI) patients with elevated high-sensitivity CRP (hsCRP)." (PMID 40528106, 2025). "The CANTOS trial pioneered the investigation of IL-1β inhibition using canakinumab, demonstrating reduced MACEs in myocardial infarction (MI) survivors with residual inflammation." (PMID 39766344, 2024). "This landmark study provided hitherto undocumented evidence that anti-inflammatory drugs targeting interleukin-1β (IL-1β) (canazumab) could effectively reduce the incidence of cardiovascular adverse events in patients with myocardial infarction, even when combined with lipid-lowering drugs." (PMID 39022620, 2024). "Therefore, interventions that inhibit NETosis, S100A8/A9, and IL‐1β during the acute inflammatory phase after myocardial infarction may exert beneficial effects on the post‐infarction inflammatory process and ventricular remodelling." (PMID 39087342, 2024). "Studies in mouse models of Alzheimer’s disease, brain injury, myocardial infarction and inflammatory bowel disease could demonstrate a reduction in expression levels of interleukin-1 beta, interleukin-6, MCP-1 and NLRP3 upon treatment with pterostilbene and prebiotics." (PMID 36906614, 2023). "For example, in heart failure (HF) induced by myocardial infarction (MI), it is possible to observe an increase in interleukin 1 beta (IL-1β), tumor necrosis factor alpha (TNF-α), interleukin 6 (IL-6), and lectin 3 levels." (PMID 36831272, 2023).
myocardial infarction (continued). "However, analysis of published scRNA-seq data indicates a rapid influx of Ccr2-expressing macrophages 1 day post myocardial infarction coincident with elevated Tnfa and Il1b expression, an event that may have been missed previously." (PMID 36271843, 2023). "Furthermore, our data indicated that Turicibacter was obviously and negatively correlated with serum cTnI and CK levels, the myocardial infarct area, HE score, apoptosis rate, inflammatory factors (IL-1β, IL-6, and TNF-α) in colon and ileum and serum LPS and Zonulin concentration." (PMID 37656700, 2023). "The expression of inflammatory factors, including tumor necrosis factor-α (TNF-α) and interleukin (IL)-1β, significantly increases after myocardial infarction (MI) in rats and has important roles in the etiology of ventricular remodeling." (PMID 35928246, 2022). "In a mouse model of acute myocardial infarction (MI), IL-1β antagonists improved LV diastolic function." (PMID 32444946, 2021). "Moreover, upstream regulation of inflammasome activation and IL-1β could be relevant as we recently reported IL-1 activation as a predictor of first-time myocardial infarction in PLWH48." (PMID 34754007, 2021). "In 2011, a multi-center CANTOS study was initiated to treat myocardial infarction (MI) survivors with monoclonal antibody against IL-1b (canakinumab)." (PMID 33801199, 2021). "In this study, we looked at cytokine levels after myocardial infarction, thus, we cannot exclude that changes of IL-1β and IL-1ra could be the results of a generalized inflammatory response to myocardial injury, thus being the consequence and not the cause of ACS." (PMID 32116755, 2020). "A total of 10,061 patients with a previous myocardial infarction and showing inflammatory residual risk (CRP > 2 mg/L) under optimal CV-protective therapy were enrolled in this randomized, double-blind trial to receive canakinumab, a IL-1β inhibitory monoclonal antibody, or a placebo every 3 months." (PMID 31652822, 2019). "IL-1β is highly expressed in cardiac tissue after acute myocardial infarction (MI), even measurable in patient's plasma the first 5 h post-MI." (PMID 31244838, 2019). "Recently, this hypothesis was confirmed in the Canakinumab Anti-inflammatory Thrombosis Outcome Study (CANTOS) trial, in which the IL-1β antagonism was able to reduce CVD in participants with previous myocardial infarction and high CRP levels, confirming the role of inflammation in CVD." (PMID 31513665, 2019). "As well, in mice with myocardial infarction, relaxin treatment after myocardial infarction for 14 days also reduces AF through the decrease on fibrosis and hypertrophy, the increase in conduction velocity, and, moreover, the decrease of the pro-inflammatory cytokine IL-1β expression." (PMID 28868039, 2017). "A key component of the inflammasome, NLRP3, plays a critical role in the secretion of IL-1β and in pyroptosis, which is an inherently inflammatory caspase 1-dependent mechanism of cell death triggered by various pathological stimuli, such as acute myocardial infarction (AMI)." (PMID 28659798, 2017). "Positive correlations have been established between acute myocardial infarction and elevated levels of pro-inflammatory cytokines such as TNF-α, IL-6, and IL-1β." (PMID 41599430, 2026). "Upon myocardial infarction, massive tissue damage and cell death resulting from ischemia activate the NLRP3 inflammasome, leading to the production of IL-1β and IL-18, which further promote adverse remodeling, ultimately contributing to heart failure (HF)." (PMID 41087719, 2025). "Post-myocardial infarction, exosomal miR-146a from transfected ADSCs directly suppressed early growth response factor 1 (EGR1) activation and IL-1β/-6 and TNF-α expression due to inhibition of the toll-like receptor 4 (TLR4)/NF-κB pathway." (PMID 40676634, 2025).
myocardial infarction (continued). "Analysis through immunohistochemistry on myocardial tissue revealed that the mVNS treatment was effective in reducing macrophage infiltration and lowering the levels of inflammatory factors (such as IL-1β and TNF-α) in the plasma post-myocardial infarction." (PMID 40001724, 2025). "In preclinical studies on conditions like myocardial infarction, heart failure, and atherosclerosis, MCC950 showed impressive results by reducing IL-1β production, decreasing neutrophil infiltration, and limiting harmful cardiac remodeling." (PMID 41226611, 2025). "In a mouse model of myocardial infarction, small interfering RNA silencing of Clec7a downregulates the expression of NLRP3, IL-1β, and IL-18, thereby attenuating myocardial injury." (PMID 40243488, 2025). "However, recent post hoc analyses from the CANTOS trial (NCT01327846) found that post-myocardial infarction patients treated with Canakinumab required significantly fewer joint replacement surgeries, suggesting that the inhibition of IL-1β may be chondroprotective." (PMID 40002768, 2025). "The findings revealed a significant upregulation in the protein and mRAN expression levels of ACSL1, IL1B, and GABARAPL1 in both the hypoxic cell model and myocardial infarction animal model compared to the control group." (PMID 40287718, 2025). "Its primary action targets IL-10, with the protein–protein interactions analysis indicating interactions between IL-10 and key inflammatory mediators—IL-1β, IFN-γ, CCL2, TNF, and TGF-β1—during acute myocardial infarction and cardiac fibrosis." (PMID 39200761, 2024). "In the acute phase (1–3 days)post-MIR in the mouse model, the infarct zone exhibits pronounced inflammation,with cytokines IL-1β and IFN-γ initiating an earlypro-inflammatory environment following myocardial infarction." (PMID 39618853, 2024). "Treatment with curcumin showed a reduction in the levels of inflammatory mediators, such as IL-6, IL-1β, and TNF-α, in the myocardium in diabetic mice with myocardial infarction." (PMID 38338960, 2024). "In contrast, exosomes from adipose-derived MSCs exhibit reduced levels of inflammatory markers as IL-1β, IL-6, TNF-α, and IFN-γ in patients with myocardial infarction." (PMID 39911664, 2024). "In humans, previous studies have shown increased expression of NLRP3 inflammasome, IL-1β, and IL-18 in patients with CAD, particularly in those with acute myocardial infarction compared with those with stable angina." (PMID 36674682, 2023). "As a result, linagliptin improved cardiac contractility, suppressed mRNAs expression of NLRP3, ASC, IL-1β, collagen I, and collagen III in the border zone of myocardial infarction, and prevented cardiac hypertrophy both in wild-type (WT) and db/db mice." (PMID 36320147, 2022). "One year after reperfusion, IL-1β was associated with impaired myocardial function and non-infarct left ventricular mass, suggesting that IL-1β could be involved in myocardial adverse remodeling and ventricular dysfunction after myocardial infarction." (PMID 36362423, 2022). "NLRP3 inflammasome activation mainly occurs in cardiac fibroblasts during myocardial remodeling and repair, activates IL-1β release and pyroptosis in cardiac fibroblasts after myocardial infarction (MI).A significant increase in expression of pyroptosis and MMP9 in cardiac fibrosis in diabetes." (PMID 35509275, 2022). "Recently, the CanakinumabAnti-inflammatory Thrombosis Outcomes Study (CANTOS) showed that blockinginflammation with the anti-IL-1β monoclonal antibody canakinumab reducedheart attacks, strokes and new-onset diabetes among patients with priormyocardial infarction (MI)." (PMID 39076182, 2022). "In the treatment of myocardial infarction, we have obtained key targets of Yixinyin, which are ALDH2, C5AR1, FOS, IL1B, TLR2, TXNRD1." (PMID 34799616, 2021).
myocardial infarction (continued). "Inhibition of IL-1B signalling has been shown to have an anti-tumour effect in the CANTOS trial, in that patients with previous myocardial infarction and high C-reactive protein levels assigned to receive Canakinumab, displayed reduced lung cancer mortality." (PMID 34290237, 2021). "The study investigates the levels of C reactive protein (CRP), interleukin 1β (IL-1β) and stromal-derived factor 1α (SDF-1α) at the time of acute myocardial infarction (AMI) and at 1 and 6 months afterwards, compared with a control group." (PMID 34180324, 2021). "Several studies have described an increased expression of proinflammatory cytokines IL-1β, IL-6, and TNF-α in ISO-induced myocardial infarction." (PMID 34072098, 2021). "Isoproterenol-induced myocardial infarction significantly amplified HSP-60 and inflammatory markers (TNF-α, IL-1β, and NFκB) as compared with normal rats." (PMID 31109132, 2019). "A comparison of the stable angina, unstable angina, and acute myocardial infarction (AMI) subgroups revealed that patients with AMI had the highest CD121a levels, although IL-1β levels were similar across all groups." (PMID 26098632, 2015). "It has been demonstrated that inflammatory cytokines, including IL-1β, IL-6, and TNF-α, increase remarkably after myocardial infarction and are involved in the subsequent left ventricular remodeling." (PMID 22792312, 2012). "Importantly, KLX can ameliorate myocardial infarction-induced cardiac damage by inhibiting the expression of the NLRP3 inflammasome, reducing the release of proinflammatory cytokines IL-1β and IL-18, and suppressing pyroptotic cell death." (PMID 40148674, 2025). "In addition, administration of L-carnitine in animal with myocardial infarction shows effects in reducing oxidative stress and enhancing antioxidant enzyme activity through the inhibition of TNF-α and IL-1β." (PMID 39283525, 2025). "In patients with prior myocardial infarction and elevated hs-CRP, canakinumab, a monoclonal antibody inhibiting IL-1β, administered every three months, significantly reduced major adverse cardiovascular events compared to placebo without materially altering LDL-C levels." (PMID 41464678, 2025). "In this study, it was found that overexpression of PLAC8 rescued the high expression of these markers, reversed the progression of myocardial infarction to heart failure, reduced cardiomyocyte injury, and lowered the expression of the inflammatory markers TNF-α and IL-1β in serum." (PMID 40471391, 2025). "In summary, we demonstrated that Coenzyme Q10 treatment can effectively promote the recovery of cardiac function after myocardial infarction and prevent its progression to heart failure, partially through inhibiting NLRP3/IL1β pathway-mediated inflammation in macrophages." (PMID 38281937, 2024). "Nevertheless, the level of proinflammatory cytokines such as TNF-α, IL-1β, IL-6, and IFN-γ was also found to be elevated in several heart diseases including congestive heart failure, atherosclerosis, coronary artery disease and myocardial infarction." (PMID 38441007, 2024). "The myocardial infarction area was significantly reduced in rats with myocardial infarction injected with KLF3-AS1 exosome, and the expressions of NLRP3, caspase-1, GSDMD, IL-1β and IL-18 in KLF3-AS1-overexpressed myocardial infarction mice were also significantly decreased." (PMID 37396588, 2023). "Targeting innate immunity with antibodies against interleukin-1 beta (IL-1β) led to reduced recurrent cardiovascular events in patients with previous myocardial infarction, independent of lipid lowering, suggesting that CVD is driven by inflammation." (PMID 37111068, 2023). "The study was the first to demonstrate that anti-inflammatory treatment by blocking pro-inflammatory IL-1β significantly reduced systemic inflammation and lowered the rate of recurrent cardiovascular events and cardiovascular death in patients with previous myocardial infarction (MI)." (PMID 36498974, 2022).